LINC02446 (long independently transcribed non-coding RNA 2446)
Gene: Long non-coding RNA gene on chromosome 12 (10,553,328 to 10,575,700, forward strand). Ensembl gene ENSG00000256039.
Diseases named in the same sentence as LINC02446 in open-access papers:
LINC02446 is named in the same sentence as 3 diseases in open-access papers, as found by Europe PMC text mining. Sharing a sentence is not in itself a finding about the gene and the disease. The quoted sentences say what the papers report.
melanoma (2 papers, 2021 to 2022). A malignant, usually aggressive tumor composed of atypical, neoplastic melanocytes. "The prognostic signature based on the OS-ireRNAs included AC009495.2, LINC02446, LINC00189, RSRP1, CUTALP, CMAHP and MOSMO, and accurately predicted the prognosis of melanoma patients, especially for those who survived for more than 3 years." (PMID 36338651, 2022). "LINC02446, LINC01857, and LINC02384 may stimulate melanoma progression by reducing tumor‐protecting miR.891a.5p and miR.203b.3p." (PMID 34159752, 2021).
COVID-19 (1 paper, 2021). A disease caused by infection with severe acute respiratory syndrome coronavirus 2. "It has been observed that increased level of LINC02207, LINC01127 was associated with the severe COVID-19 group, whereas LINC02084, LINC02446, LINC00861, LINC01871, and ANKRD44-AS1 were associated with the mild COVID-19 group." (PMID 34940755, 2021).
tumor (2 papers, 2021 to 2023). "Finally, quantitative RT-PCR showed that AC005261.1, AC021321.1, AL024508.2, LINC02446 and LINC01106 were lowly expressed in tumor cells, while ARHGAP5-AS1 showed the opposite trend." (PMID 37424068, 2023). "In addition, we revealed that LINC01857, LINC02446, and LINC02384, as competing endogenous RNAs (ceRNAs) of IL2RA and IL7R, were oncogenes, while miR‐203b‐3p and miR‐891a‐5p, as microRNA sponges of IL2RA and IL7R, respectively, act as potential tumor suppressor molecules." (PMID 34159752, 2021).